JDP2 (Jun dimerization protein 2)
Diseases named in the same sentence as JDP2 in open-access papers (continued):
Sharing a sentence is not in itself a finding about the gene and the disease.
cancer (continued). "Given that DR5 plays an important role in TRAIL‐mediated cancer cell apoptosis, we next investigated whether JDP2 affects TRAIL sensitivity of cancer cells." (PMID 33108704, 2020). "Further studies are needed to confirm whether JDP2 is a potential therapeutic target for TRAIL‐mediated cancer immunotherapy." (PMID 33108704, 2020). "Several studies have shown that JDP2 is also involved in cancer development and progression." (PMID 28146118, 2017). "Whereas much is known regarding JDP2 expression within cancer cells, the role of JDP2 in the stroma and how it affects cancer growth and metastasis is largely unknown." (PMID 26497998, 2015). "Whereas the role of JDP2 expression within cancer cells has been studied, its role in stromal cells at the tumor microenvironment is largely unknown." (PMID 26497998, 2015). "Here, using mice harboring a homozygous mutation in the JDP2 allele, we characterized the role of JDP2 expression in non-cancer cells on cancer development and metastasis." (PMID 26497998, 2015). "However these iPSC-like cells caused cancer although they showed stemness characteristics, indicating that JDP2 controls the nature of iPSCs and their ability to develop into cancer stem cell-like cells." (PMID 24202329, 2013). "How does JDP2 induce the cancer phenotype during reprogramming?" (PMID 24202329, 2013). "We also discuss the role of JDP2 in cancer cell reprogramming and ROS homeostasis." (PMID 24202329, 2013). "Moreover, the AP-1 repressor, JDP2, plays a dual role in the reprogramming of cancer cells." (PMID 35629138, 2022). "However, some studies have shown that JDP2 can potentiate cancer cell growth." (PMID 24202329, 2013). "After being modified by the phosphorylation, the activated TF JDP2 would upregulate the DNA-methylated target gene IL6, which leads to promoting cell apoptosis and immune response against cancer." (PMID 35743172, 2022). "Curiously, knockdown of JDP2 increases the sensitivity of cells to TNF‐related apoptosis‐inducing ligand (TRAIL), which induces apoptosis in cancer cells through DR4 and DR5." (PMID 33108704, 2020). "While the basal SDF-1 levels are transcriptionally regulated by ATF3 and JDP2, the potentiation of SDF-1 secretion following co-culture with cancer cells is most likely controlled post-transcriptionally." (PMID 30670778, 2019). "While the tumor compromises both cancer cells and stroma, here we studied the role of ATF3 and JDP2 in the stroma." (PMID 30670778, 2019). "Next, to assess the role of CCL5 on cancer cell invasion, we added neutralizing CCL5 antibodies or a control antibody into CM derived from wild-type and JDP2 −/− BMDCs." (PMID 26497998, 2015). "Our data demonstarted that 2F such as JDP2 and OCT4 generated the cancer stem-like cells with stemness-characteristics." (PMID 24202329, 2013). "JDP2 and OCT4 reprogram cancer cells into iPSC-like cells 146,147." (PMID 40765830, 2025). "We also functionally showed that Nr2f6 and JDP2 may contribute to differential expression of many ELI-D1 genes, and may contribute to increased stromal vulnerability to placental, and cancer malignancy in hemochorial vs epitheliochorial species." (PMID 40847025, 2025). "The expression of JDP2 may promote cancer progression through Wnt signaling activation and induce CSC characteristics in cancer cells." (PMID 38791215, 2024). "Given that JDP2 is known as an epigenetic modulator, it may contribute to TRAIL resistance in cancer cells by suppressing DR4 and DR5 expression." (PMID 33108704, 2020). "Furthermore, ATF3 and JDP2 were found to regulate SDF-1 transcription and secretion in fibroblasts, a phenomenon that is potentiated in the presence of cancer cells." (PMID 30670778, 2019).
cancer (continued). "Treatment with OICR-9429, a small-molecule antagonist of the WDR5-MLL interaction, inhibits the β-catenin/JDP2/PRMT5 complex-reestablished GSH metabolism, leading to a lethal increase in the already-elevated levels of ROS in the genotoxic-agent treated cancer cells." (PMID 31434880, 2019). "In conclusion, this study shows that JDP2 functions as a negative feedback regulator of the ATF4 pathway and modulates TRAIL sensitivity in cancer cells." (PMID 33108704, 2020). "Fibroblasts were the major stromal component responsible for the increased tumor growth, since co-implantation of cancer cells with MEFs lacking both ATF3 and JDP2 was able to mimic the tumor growth phenotype developed in dKO mice." (PMID 30670778, 2019).
tumor (28 papers, 2010 to 2025). "For example, JDP2 inhibits cell transformation by acting as a tumor suppressor in severe combined immune-deficient mice." (PMID 38473360, 2024). "Decreased expression of JDP2 is associated with tumor metastasis and an unfavorable prognosis factor in patients with pancreatic cancers." (PMID 38473360, 2024). "JDP2 was reported to be downregulated in PC tissues and its downregulation is associated with tumor metastasis and poor prognosis in patients with PC." (PMID 35584452, 2022). "Collectively, these results indicate that the double deficiency in ATF3 and JDP2 specifically affects fibroblasts in the tumor environment and the function of tumor vasculature, possibly leading to changes in tumor development and size." (PMID 30670778, 2019). "Down-regulation of JDP2 is associated with tumor metastasis and poor prognosis in patients with pancreatic carcinoma." (PMID 28146118, 2017). "For example, in a severe combined immune-deficient mice study, JDP2 inhibited cell transformation and acted as a tumor suppressor." (PMID 28146118, 2017). "The replacement of wild-type bone marrow derived cells (BMDCs) with JDP2-deficient BMDCs recapitulates the metastatic phenotype of JDP2−/− tumor-bearing mice." (PMID 26497998, 2015). "JDP2, more prominent in apCAFs, has been shown to impede tumor growth by modulating SDF-1 transcription in CAFs." (PMID 39112478, 2024). "The transcriptional modulator Jun dimerization protein 2 (JDP2) is closely related to tumour differentiation and apoptosis and participates in the regulation of CD8+ T cell immune function." (PMID 38168553, 2024). "The tumor-forming ability of these partially reprogrammed gastric CSC-like cells is reduced in immune-deficient mice, which shows that JDP2 plays a critical role in the reduction of oncogenic potential." (PMID 32493501, 2020). "In our experimental model, we found that tumor growth was significantly higher in the dKO mice than WT mice, indicating that ATF3 and JDP2 expression by host cells contribute to the primary tumor fate." (PMID 30670778, 2019). "We identified that the deficiency of ATF3 and JDP2 elevates stromal cell-derived factor 1 (SDF-1) secretion by CAFs found in the tumor stroma, ultimately increasing tumor growth." (PMID 30670778, 2019). "Collectively, our results suggest that ATF3 and JDP2 regulate the expression of essential tumor promoting factors expressed by fibroblasts within the tumor microenvironment, and thus restrain tumor growth." (PMID 30670778, 2019). "Collectively, our results suggest that the expression of ATF3 and JDP2 in stromal cells, and specifically fibroblasts, can regulate tumor growth." (PMID 30670778, 2019). "As ATF3 and JDP2 compensate each other’s function, we studied the double deficiency of ATF3 and JDP2 in the stromal tumor microenvironment." (PMID 30670778, 2019). "Our data in cell lines convincingly indicate a role for JDP2 in maintaining tumor cell survival, but its ability to initiate T-ALL remained in question." (PMID 29941549, 2018). "Coexpression of jdp2 with murine c-Myc led to a marked increase in tumor penetrance, with 80% of fish exhibiting T-ALL at 120 d, compared with 40% when c-Myc was expressed alone (P = 0.001)." (PMID 29941549, 2018). "When tumor cells harvested from Tg(rag2:jdp2) fish were injected into the circulation of 2-d-old rag2E450fs (Casper) mutant embryos, they rapidly migrated to and engrafted in the thymus of recipient larvae, consistent with their thymic origin." (PMID 29941549, 2018). "We thus coinjected single-cell embryos with rag2:mCherry, rag2:mCherry/rag2:Myc, or rag2:mCherry/rag2:Myc/rag2:jdp2 and monitored the fish by fluorescent microscopy for tumor onset." (PMID 29941549, 2018).
tumor (continued). "To evaluate the role of Jdp2 in tumor maintenance we used an shRNA construct to knockdown the levels of Jdp2 in a Dnmt3a-deficient MYC-induced PTCL cell line." (PMID 27690235, 2016). "Mainly, BMDCs expressing JDP2 home in large numbers to the tumor site and contribute to the secretion of the pro-metastatic CCL5 cytokine, leading to metastasis." (PMID 26497998, 2015). "Here we focused on the expression of the c-Jun dimerization protein, 2 (JDP2) transcription repressor in the host and studied the effect of JDP2 ablation on tumor and metastatic growth." (PMID 26497998, 2015). "We found that JDP2 expression in the host suppresses primary tumor growth; however, it promotes metastatic spread." (PMID 26497998, 2015). "Overall, this study suggests that JDP2-expressing BMDCs within the tumor microenvironment contribute to metastatic spread." (PMID 26497998, 2015). "Collectively, these results indicate that CCL5 in JDP2 expressing BMDCs is necessary and sufficient for tumor cell invasion." (PMID 26497998, 2015). "Collectively, the data suggests that a dramatic increase in the expression of key regulatory proteins occurs in JDP2-transgenic mice during the tumor promotion stage." (PMID 20214788, 2010). "Furthermore, JDP2 is involved in multiple processes/functions, including cell growth, cellular senescence, cell death, tumor control and enhancement, stemness, and pluripotent capacity." (PMID 40765830, 2025). "Inhibition of Jdp2 expression significantly increased the growth of tumors but could be rescued by AhR overexpression, which suggested that Jdp2 acts as a tumor suppressor upstream of the AhR-Nrf2 gene battery." (PMID 37596694, 2023). "This suggests that the function of JDP2 in tumor formation may change depending on physiological and pathological situations." (PMID 33108704, 2020). "Therefore, identifying molecules that increase the expression of ATF3 and JDP2 can be used to control tumor growth and metastasis spread." (PMID 30670778, 2019). "Taken together, our study reveals a new role for JDP2 in the tumor stroma." (PMID 26497998, 2015). "One possible explanation for the increase in disease severity in JDP2-transgenic mice might be that JDP2 expression potentiates tumor initiation." (PMID 20214788, 2010). "The inhibitory effect of JDP2 on oncogenic AP‐1 suggests that JDP2 may be a tumor suppressor." (PMID 33108704, 2020). "Thus, it appears likely that Wnt-independent effects of ICG-001 may at least partially be mediated through upregulation of p21, Gadd45A, and JDP2, resulting in strong impairment of tumor-specific features in pedHGG cells." (PMID 28460484, 2017). "From our findings, three (GPR6, GRASP, JDP2) of the six validated genes of phase A are related to EMT and tumor migration; one validated gene (GNPDA1) links to the glycolytic pathway and glycosylation." (PMID 35563509, 2022). "By contrast, the present study suggests that JDP2 negatively regulates TRAIL/DR5 signaling and promotes tumor cell survival." (PMID 33108704, 2020). "However, it remains controversial whether JDP2 is a tumor suppressor or oncogenic factor." (PMID 33108704, 2020). "While tumor size in ATF3-KO mice was similar to WT mice, the tumors developed in JDP2-KO mice were significantly larger, consistent with previous publications." (PMID 30670778, 2019).
tumor (continued). "To investigate the impact of host JDP2 and ATF3 expression on tumor growth and proliferation, we generated mice with double deficiency of these proteins by consecutive crossing of JDP2−/− and ATF3−/− strains." (PMID 30670778, 2019). "This suggested that liver damage and tumor initiation is alike in mice independent of JDP2 expression." (PMID 20214788, 2010). "We therefore initially hypothesized that tumor metastasis will be significantly abrogated in mice lacking both ATF3 and JDP2, as both transcription factors compensate for the loss of each other." (PMID 30670778, 2019). "However, decrease in the levels of Jdp2 in this cell line did not affect cellular growth, suggesting Jdp2 is not required for tumor maintenance in such setting." (PMID 27690235, 2016). "To examine whether or not JDP2 has an effect at the tumor initiation stage, we tested the expression of genes 24 h following DEN injection." (PMID 20214788, 2010). "Since JDP2 and ATF3 may compensate for one another in the absence of their counterpart, we examined the effect of double deficiency of ATF3 and JDP2 (dKO) on tumor growth and metastasis." (PMID 30670778, 2019). "Thus, fibroblasts lacking JDP2 and ATF3 expression, promote tumor growth and blood vessel perfusion." (PMID 30670778, 2019). "We asked whether each one of these components contributes to tumor growth in the absence of ATF3 and JDP2 expression." (PMID 30670778, 2019).
bacterial infection (1 paper, 2022). "It is well known that neutrophils are the first line of defense against bacterial infection, and bacteria tend to downregulate the transcription factor from the AP-1 family, Jdp2, which inhibited neutrophil maturation." (PMID 35242136, 2022).
cardiac disease (1 paper, 2019). "Among these, cardiac disease is a model that we have been using to investigate JDP2 and ATF3." (PMID 30818334, 2019).
JDP2 also shares sentences with these, for which no sentence is quoted: neuroblastoma (2 papers); scrub typhus (2); acute lymphoblastic leukemia (1); bladder cancer (1); brain tumors (1); cardiovascular diseases (1); colorectal cancer (1); genetic diseases (1); glioblastoma (1); hypertrophy (1); infection (1); ischemic stroke (1); latent infection (1); metabolic syndrome (1); pancreatic adenocarcinoma (1); post-traumatic stress disorder (1); preeclampsia (1); proliferative vitreoretinopathy (1); T-cell acute lymphoblastic leukemia (1); Ventricular hypertrophy (1); viral infection (1).